NLRP3 (NLR family pyrin domain containing 3)
Diseases named in the same sentence as NLRP3 in open-access papers (continued):
Sharing a sentence is not in itself a finding about the gene and the disease.
liver fibrosis (continued). "NLRP3 inflammasome is involved in the fibrosis process of various organs or tissue, such as kidney fibrosis, pulmonary fibrosis, liver fibrosis, and cardiac fibrosis." (PMID 32850832, 2020). "Studies have shown that wild type mice develop more severe liver fibrosis induced by carbon tetrachloride (CCL4) as compared to the NLRP3–/– and ASC–/– mice, as evidenced by higher α-SMA expression and more Sirius Red staining area in the wild-type than in the knockout mice." (PMID 32211410, 2020). "Taken together, we hypothesize that oridonin attenuates liver fibrosis in vitro via the inhibition of the NLRP3 inflammasome." (PMID 32219880, 2020). "Furthermore, many different observations have suggested that NLRP3 is also involved in NASH-liver fibrosis evolution: the deletion of the NLRP3 gene or the pharmacological blockade of NLRP3 inflammasome reduced liver fibrosis in animal models of NAFLD/NASH." (PMID 32331389, 2020). "We speculate that NF-κB might be downstream of NLRP3 inflammasome, which then participates in NLRP3 inflammasome-induced liver fibrosis in mice infected with S. japonicum." (PMID 30635040, 2019). "NLRP3 inflammasome activation subsequently aggravates liver fibrosis and cholestasis." (PMID 31827690, 2019). "MRS treatment could reduce activation of the NLRP3 inflammasome signal pathway and inhibit pyroptosis, thus reducing liver fibrosis in BDL rats." (PMID 31827690, 2019). "NLRP3 is a major proinflammatory “danger” receptor and we wished to determine whether it was responsible for liver fibrosis." (PMID 30635040, 2019). "In the future, we may further explore whether there are other signaling pathways involved in NLRP3 inflammasome induced liver fibrosis following S. japonicum infection." (PMID 30635040, 2019). "Matrine prevented MCD diet-induced inflammation and fibrosis in the liver after 6 weeks of treatment, as demonstrated by a matrine-induced suppression of the increases in TNFα, CD68, MCP-1 and NLRP3, and hepatic fibrosis proteins (TGFβ, Smad3, and collagen 1) induced by MCD diet." (PMID 31068812, 2019). "Surprisingly, NLRP3 inflammasome was involved in liver fibrosis mostly from KCs." (PMID 30635040, 2019). "However, the question of which cells are responsible for NLRP3 inflammasome-mediated liver fibrosis remains unanswered." (PMID 30635040, 2019). "NLRP3 inflammasome activation is correlated with liver fibrosis during BDL." (PMID 31827690, 2019). "Collectively, NLRP3 inflammasome pathway appears to be central to the pathogenesis of liver fibrosis, and this uncovered link may open avenues for novel therapeutics for liver fibrosis." (PMID 30319645, 2018). "Since previous studies have shown that the formation and activation of NLRP3 inflammasomes in fibroblasts including HSCs may trigger the development of liver fibrosis, we determined whether these inflammasome-triggered fibrogenetic effects occur in NAFLD." (PMID 30140364, 2018). "In addition to the direct effect on innate immunity, NLRP3 inflammasome has an essential role in shaping adaptive immune responses in liver fibrosis." (PMID 30319645, 2018). "In other liver fibrotic animal models such as alcoholic steatosis and cirrhosis, viral hepatitis-induced cirrhosis and hepatic fibrosis during Schistosoma J infection, NLRP3 inflammasome activation has also been reported to either trigger or modulate hepatic inflammation leading to fibrosis." (PMID 30140364, 2018). "Our results demonstrated that NLRP3 inflammasomes serve as an intracellular inflammatory machinery in HSCs, which may turn on the inflammatory response and thereby instigate liver fibrosis during Schistosoma J. infection." (PMID 27322427, 2016). "Furthermore, in vivo inhibition of NLRP3 inflammasome with caspase-1 inhibitor dramatically decreased mature IL-1β level of liver tissue and ameliorated liver fibrosis in bile duct ligation (BDL) mouse model." (PMID 27924062, 2016).
liver fibrosis (continued). "Common features of the top three pathways for KD (Trem1 signaling, Hepatic fibrosis, and IL-10 signaling) and the other groups were the abundance of transcripts related to the activation of the Nlrp3 inflammasome, including Il-1 and caspase-1 related transcripts." (PMID 25614765, 2014). "The altered structure of gut microbiota in the CCl4 group and NLRP3−/−+CCl4 mice suggested that NLRP3 might exert its pro-inflammatory role via altering the activity of signaling pathways and ECs in the gut microbiota to facilitate the development of liver fibrosis." (PMID 40689656, 2025). "Furthermore, bile acids can activate the NLRP3 inflammasome to induce liver fibrosis (8, –, 10)." (PMID 40689656, 2025). "Therefore, the modulation of autophagy and NLRP3 inflammasomes may be defined as a treatment target for liver fibrosis." (PMID 38182564, 2024). "Furthermore, activation of the NLRP3 inflammasome in hepatic stellate and Kupffer cells may initiate the inflammatory response to induce pyroptosis and liver fibrosis during schistosoma infection." (PMID 39679172, 2024). "Their role as resolving effector cells in liver fibrosis that induce pro-inflammatory macrophages into a restorative phenotype and thereby reversing inflammation once the injury trigger ceases is potentially exerted via miR-223, a critical negative regulator of NLRP3." (PMID 37664463, 2023). "In addition, NLRP3−/− mouse models have reduced levels of liver fibrosis." (PMID 37446339, 2023). "In bile duct ligation (BDL) mice, toxic bile acids further activate NLRP3 inflammasome assembly and cause Kupffer cells to develop the M1 phenotype, leading to the production of proinflammatory cytokines, including IL-6, TNF, and IL-1β, which aggravate liver fibrosis and damage." (PMID 36969233, 2023). "In addition, the activation of NLRP3 inflammasome leads to pyroptotic cell death of hepatocytes to release NLRP3 inflammasome particles, which are internalized by adjacent hepatic stellate cells, activating them to induce liver fibrosis." (PMID 35565726, 2022). "In addition, the NLRP3 inhibitor MCC950 treatment reduced the development of liver fibrosis in CCl4-induced liver fibrosis mouse models, indicating that blocking NLRP3 inflammasome-dependent pyroptosis may be a promising therapeutic strategy." (PMID 36429008, 2022). "Inhibition of TGF-β-related factors or NLRP3 inflammasome may play an important role in breaking the vicious cycle and are recommended as therapeutic targets for the progression and treatment of liver fibrosis." (PMID 35138513, 2022). "A hypothesis is raised here that the mechanism of coffee’s beneficial effects on prevention of HCC relies on the capability of caffeine in suppressing NLRP3 inflammasome activation and the ensuing inflammatory process, pyroptosis, hepatic fibrosis, and cirrhosis." (PMID 36330474, 2022). "Therefore, targeting the NLRP3 inflammasome may be a promising approach for the development of therapies for TGF-β-induced liver fibrosis." (PMID 35138513, 2022). "Nevertheless, the primary occurrence of NLRP3 inflammasome-dependent pyroptosis in which type of cells (hepatocytes, KCs or HSCs), the detailed molecular mechanism regarding how pyroptosis occurs, and its clinical importance during liver fibrosis progression, are still unclear." (PMID 36429008, 2022). "However, it is unclear whether SSd or estrogen alleviates liver fibrosis by inhibiting the expression of NLRP3 inflammasome proteins via activating the ERβ pathway." (PMID 35694250, 2022). "However, the role of the NOX4/NLRP3 signaling pathway in liver fibrosis has rarely been studied." (PMID 34530693, 2021). "Studies have shown α-SMA and NLRP3 double positivity in human liver fibrosis specimens, where the expression level of NLRP3 is significantly increased compared with that in normal liver tissues, suggesting that the NLRP3 inflammasome is involved in the regulation of hepatic fibrosis." (PMID 34944017, 2021).
liver fibrosis (continued). "In summary, the present study demonstrated that deAND may reduce steatohepatitis, liver fibrosis and liver injury, upregulate Nrf-2 triggered increase in proteins and/or activities of antioxidant enzymes, and lower inflammation by attenuating NLRP3 inflammasome activation in mice fed a HFHC diet." (PMID 32085637, 2020). "In mice with alcoholic steatohepatitis, andrographolide improves the liver fibrosis, decreases the hepatic fibrogenic proteins, such as connective tissue growth factor, collagen type I, alpha 1 chain and collagen IV, and suppresses the NLRP3 inflammasome activation." (PMID 33390969, 2020). "p66Shc, a redox enzyme that regulates mitochondrial ROS generation, contributes to hepatic fibrosis, whereas its inhibition can ameliorate the liver fibrosis through restraining the activation of HSCs via down-regulating mitochondrial ROS production and NLRP3 expression." (PMID 32963808, 2020). "The NLRP3 inflammasome complex can be overactivated, producing an aggravated inflammatory process, after chronic damage, such as metabolic disturbances that occur during NAFLD and liver fibrosis, or during a process of progressive deterioration associated with aging." (PMID 32977490, 2020). "Although there are reports that in chronic liver disease oxidative stress has a clear role in HSC activation triggering fibrotic process, the results from the present study are the first to clarify that local oxidative stress may induce HSC activation and liver fibrosis through NLRP3 inflammasomes." (PMID 30140364, 2018). "A438079, a specific inhibitor of P2X7 that acts as a trigger for NLRP3 inflammasomes, attenuates CCL4-induced hepatic fibrosis in mice by downregulating smooth muscle α-actin and TGF-β1 expression and reducing hepatic collagen formation." (PMID 40667485, 2025). "However, it is unclear whether NLRP3 has an impact on BA metabolism in liver fibrosis." (PMID 40689656, 2025). "This is important as NLRP3 can be antagonized by various drugs such as MCC950, which specifically neutralizes NLRP3 and has been shown to improve MASH pathology, including inflammation and liver fibrosis." (PMID 38672492, 2024). "The findings of the current study provide new evidence supporting the important role of NLRP3 inflammasomes in MAFLD pathogenesis and highlight their potential for early detection of post-MAFLD liver fibrosis." (PMID 39179677, 2024). "To further determine whether elevated GCDCA can cause liver fibrosis in vivo and the role of NLRP3 in the progression of liver fibrosis, we used GCDCA gavage and CCl4 intraperitoneal injection intervention, and the results showed that both of them could induce liver fibrosis in mice." (PMID 38172440, 2024). "It is well documented that the activation of the NLRP3 inflammasome/IL-1β axis can lead to pyroptosis of HSC, thereby exacerbating liver injury and eventually leading to hepatic fibrosis." (PMID 39372196, 2024). "Univariate regression analysis showed that low mean relative gene expression levels of IL-1β (p < 0.001) and NLRP3 (p = 0.017), and high NFS (p = 0.004) were independent factors for hepatic fibrosis in MAFLD patients." (PMID 39179677, 2024). "The latest research shows that TREM2+LAMs can inhibit NLRP3 activation and pro-inflammatory cytokine secretion, then degrade the ECM in the liver, thereby accelerating the regression of liver fibrosis." (PMID 39635524, 2024). "To demonstrate the role of the NLRP3 inflammasome in activating liver fibrosis, we infected LX2 cells with lentivirus with NLRP3 knockdown and showed that GCDCA-induced liver fibrosis markers were significantly reduced after shNLRP3." (PMID 38172440, 2024). "In the current study, we compared the expression levels of NLRP3 and IL-1β in MAFLD individuals with varying degrees of hepatic fibrosis and steatosis and found a considerable lowering in their expression levels was linked to advanced fibrosis." (PMID 39179677, 2024).
liver fibrosis (continued). "In an aging mouse model, chronic‐plus‐binge alcohol feeding‐induced liver fibrosis was attenuated by treatment with MCC950, a selective NLRP3 inhibitor." (PMID 36999514, 2023). "Mechanistically, EGCG was revealed to repress the activation of macrophage NLRP3 inflammasome, a critical trigger of HBV-induced liver fibrosis." (PMID 37122751, 2023). "Inhibition of NLRP3 by MCC950 ameliorates age‐ and alcohol‐induced liver fibrosis by decreasing inflammatory cell infiltration and hepatocyte‐derived stress signaling—ASK1 and HMGB1." (PMID 36999514, 2023). "Deletion of SIRT1 in hepatocytes enhances NLRP3 signaling and triggers HSC activation and liver fibrosis in young mice in response to liver injury." (PMID 36999514, 2023). "The downregulation of NLRP3 attenuated HSC activation and liver fibrosis, suggesting that the upregulation of NLRP3 was an intrinsic response of HSC and was necessary for HSC activation." (PMID 36983568, 2023). "Asp was found to antagonize liver fibrosis by inhibiting HSC proliferation and activation and boosting cell apoptosis and to block the NF-κB/NLRP3 inflammasome signaling pathway in HSCs by upregulating the expression of NS3TP1." (PMID 36983568, 2023). "First, NLRP3 inhibition by MCC950 effectively suppresses IL‐1β expression, inflammatory cell infiltration, and liver fibrosis in alcohol‐fed old mice." (PMID 36999514, 2023). "NLRP3 inhibition by MCC950 ameliorates age‐ and alcohol‐induced liver fibrosis likely by reducing inflammatory cell infiltration and suppressing hepatocyte‐derived danger signaling." (PMID 36999514, 2023). "RA curbs NLRP3 formation in PBC mice and inhibits its cascading inflammatory pathway, allaying the degree of liver injury and liver fibrosis in PBC mice." (PMID 35195182, 2022). "In conclusion, S100A8-mediated NLRP3 inflammasome-dependent pyroptosis by TLR4/NF-κB activation and ROS production in macrophages facilitates liver fibrosis progression." (PMID 36429008, 2022). "NLRP3 inflammasomes play a pivotal role in FLD, especially in the progression of chronic types, including NAFLD, ALD, and liver fibrosis." (PMID 36160411, 2022). "Several studies have reported the critical role of NLRP3 inflammasome in mediating EMT and TGF-β1 signalling in renal and liver fibrosis." (PMID 35596212, 2022). "Additionally, studies have shown that the NLRP3 inflammasome is directly implicated in the development of liver fibrosis and may be directly expressed and activated in HSCs without the need for cytokines." (PMID 36110858, 2022). "As regards the extent of liver fibrosis, the sensitivity, specificity, PPV, NPV, and accuracy of serum NLRP3, APRI, and FIB-4 were determined to distinguish advanced fibrosis/cirrhosis (F3-F4) from early fibrosis (F1-F2)." (PMID 36376416, 2022). "Gardenoside can ameliorate lipid deposition and liver fibrosis, and has been shown to decrease the expression levels of dipeptidyl peptidase-4 (DPP4), CCCTC-binding factor (CTCF), NLRP3, ASC, caspase-1 p20, GSDMD-N, and IL-1β in vitro and in vivo NAFLD models." (PMID 36016562, 2022). "By reducing the activity and expression of NOX/ pyrin-domain-containing 3 (NLRP3) inflammasome signaling, UA suppresses HSC activation and reverses liver fibrosis." (PMID 36290765, 2022). "Therefore, NLRP3 inflammasome is closely associated with the function of inflammatory cytokines in NAFLD and may be a key point in the progression of hepatic steatosis to NASH and hepatic fibrosis." (PMID 35603224, 2022). "In summary, these studies have demonstrated that hepatocellular NLRP3 inflammasome and pyroptosis contribute to the development of NAFLD and liver fibrosis via the cross-talk between hepatocytes and HSCs." (PMID 35707547, 2022). "In animal experiments, we also confirmed that DNTs promoted liver fibrosis progression and significantly increased collagen and collagen fiber expression in cells, while MCC950 (NLRP3 inhibitor) treatment suppressed the effect of DNTs." (PMID 35371052, 2022).
liver fibrosis (continued). "The activation of NLRP3 has been shown to promote the secretion of α-SMA and type I collagen as well as other fibrosis markers to promote liver fibrosis, thus promoting the occurrence of hepatocellular carcinoma." (PMID 35846123, 2022). "Study results demonstrated that 25-OCH3-PPD has a hepatoprotective effect against liver fibrosis and reduces inflammation by regulating P2X7R-mediated NLRP3 inflammasome." (PMID 35276849, 2022). "Liver fibrosis levels were flagrantly higher (p<0.01), and TNF-α, NOD-like receptor protein 3 (NLRP3), caspase-1, interleukin-18 (IL-18), and interleukin-1β (IL-1β) protein or gene expression were manifestly up-regulated (p<0.01)." (PMID 35195182, 2022). "The taurine pathway plays an antioxidant role in acute liver failure, and it can inhibit liver injury and liver fibrosis by inhibiting TLR4/NFKB and and TxNiP/NLRP3 pathways." (PMID 36278176, 2022). "UA alleviated liver fibrosis, which manifested as decreases in collagen deposition, liver injury, and the expression of fibrosis-related factors, and the expression of NOX4 and NLRP3 was significantly inhibited by UA treatment." (PMID 34530693, 2021). "The IHC results showed that the expression of NOX4 and NLRP3 was upregulated in mice with CCI4 induced liver fibrosis, and after UA treatment, the expression of NOX4 and NLRP3 was significantly reduced (P < .050)." (PMID 34530693, 2021). "Based on animal models of liver fibrosis, we explored the effect of intestinal bacteria during liver fibrosis and the effect of NOX4/NLRP3 inflammasome signal." (PMID 34530693, 2021). "Therefore, it is concluded that the activation of NLRP3 inflammatory bodies mediated by P2X7R may be involved in the production of IL-1β in hepatic stellate cells, and blocking the axis of P2X7R-NLRP3 inflammatory bodies may be a potential target for the treatment of hepatic fibrosis." (PMID 35002763, 2021). "NLRP3 inflammasome has been demonstrated to play a significant role in NAFLD and liver fibrosis/cirrhosis." (PMID 32211410, 2020). "Evidence indicates that activation of NLRP3 inflammasome can lead to HSC activation and liver fibrosis." (PMID 32873229, 2020). "Accumulated evidences have already demonstrated that NLRP3 inflammasome participates in the pathogenesis of liver diseases like NAFLD, liver fibrosis, cirrhosis, and HCC." (PMID 32211410, 2020). "Upregulation of IL-16 and IL-17 is mediated by the NF-κB pathway, and maturation of IL-1β via the NLRP3 inflammasome triggers HSC activation with the consequent deposition of an increased amount of ECM, producing liver fibrosis." (PMID 33333846, 2020). "In support of this data, chenodeoxycholic acid has been shown to induce NLRP3 activation in macrophages and Kupffer cells, possibly through TGR5/EGFR-dependent ROS formation, and to contribute to the liver fibrosis in the bile duct ligation murine model." (PMID 32192118, 2020). "Accumulating evidences have revealed the critical role of NLRP3 inflammasome in the development of several liver diseases including NAFLD, liver fibrosis and acute liver injury." (PMID 33536915, 2020). "Components of the NLRP3 inflammasome and ASC are present in HSCs and play potential roles in HSC activation and liver fibrosis development." (PMID 33333846, 2020). "Recently, a study highlighted the direct role of the NLRP3 inflammasome in HSC activation, which directly triggers liver fibrosis." (PMID 32296329, 2020). "This then activates HSCs accompanied by NLRP3 inflammasome activation, and then results in ECM deposition and liver fibrosis." (PMID 30635040, 2019).